HNF4A (hepatocyte nuclear factor 4 alpha)
Diseases named in the same sentence as HNF4A in open-access papers (continued):
Sharing a sentence is not in itself a finding about the gene and the disease.
cancer (continued). "Antibodies specific to either P1-HNF4α or P2-HNF4α revealed that AML12 cells also do not express detectable P2-HNF4α, while all the HNF4α-positive cancer lines do." (PMID 30341289, 2018). "While BMAL1 and HNF4α are co-expressed in healthy hepatocytes and nontransformed hepatocyte-derived cell lines, we found that cancer cells expressing P1/P2-HNF4α express little to no BMAL1." (PMID 30341289, 2018). "Furthermore, 72 cases of ccRCC patients with cancer and corresponding adjacent tissues in database GEO were used to verify the relationship among VHL, HNF-4α and ALDH2." (PMID 28643803, 2017). "A direct correlation between hepatic HNF4-α and SHBG mRNA levels has been also observed in cancer patients, in whom hepatic HNF4-α and SHBG mRNA levels were reported to be inversely related to hepatic triglyceride levels and to decrease in relation to body mass index." (PMID 27113851, 2016). "Importantly, forced expression of HNF-4α dramatically inhibits the epithelial mesenchymal transition (EMT) of hepatocyte, generation of the cancer stem/progenitor cells and proliferation of HCC cells, thus preventing hepatocarcinogenesis in rats." (PMID 25238230, 2014). "Elevated Hepatocyte nuclear factor 4 alpha (HNF4α) then trapped β-catenin at the membrane, lowered TCF reporter constructs for Wnt/β-catenin signaling (TOP/FOP) luciferase output, and reduced the activity of several genes involved in cancer progression (including AXIN2, CCND2, RUNX2, and MMP3)." (PMID 41149627, 2025). "However, no overexpression assay on HNF4A was performed to mimic its elevated expression in cancer cells." (PMID 34595169, 2021). "Moreover, NF-κB was found to upregulate the expression of miR-21 and inhibit that of HNF4α, thereby forming an HNF4α-NF-κB negative feedback regulatory loop to regulate the course of cancer." (PMID 33462379, 2021). "Recently, it has been shown that HNF4α is involved in abnormal activation of one or more signaling pathways (such as the nuclear factor-κB (NF-κB) pathway, Wnt/β-catenin pathway, and STAT pathway), playing a pivotal role in the occurrence and progression of cancer." (PMID 33462379, 2021). "Thus, whether HNF4α is a friend or a foe in CRC is puzzling, and future studies are needed to elucidate its role in cancer and to make it an actionable target for cancer treatment." (PMID 34771521, 2021). "Using the 5 patients with both normal and cancer cells profiled, we estimated the frequency of inactivation of all 56 colon-specific TFs across the 5 patients, which revealed that CDX2 and TRIM31 were inactivated in 80% of the patients, whereas ATOH1, HNF4A, CDX1, and TBX10 were inactivated in 60%." (PMID 33083012, 2020). "In these cancer tissues, HNF4α was low expressed compared with adjacent normal tissues." (PMID 30405404, 2018). "Four transcription factors, EGR1, HNF4A, MITF and FOXA2, appeared to form a hub of upstream regulators in all five gene-sets (p < 0.001) and could explain the apparent overlap in disease outcomes (ie. cancer)." (PMID 28531178, 2017). "In addition, we detected some other ‘cancer stemness’ markers (e.g. LGR4, SOX9, KLF5, MET) as well as pancreatic embryogenesis-related factors which may be re-initiated in CSC (e.g. HNF4A)." (PMID 24069258, 2013). "Consistent with the expression pattern of the other epithelial marker HNF4α and CK19, undifferentiated carcinoma cells lacked E-cadherin expression." (PMID 27323406, 2016). "Hepatocyte nuclear factor 4 alpha (HNF4α), a nuclear marker for mature hepatocytes, was strongly expressed in normal hepatocytes and well differentiated HCC, whereas undifferentiated carcinomas showed almost no expression." (PMID 27323406, 2016).
infection (31 papers, 2010 to 2025). The state of being infected such as from the introduction of a foreign agent such as serum, vaccine, antigenic substance or organism. "In in vivo zebrafish models, hnf4α-deficient larvae showed profound susceptibility, with survival rates reduced by 13.33–40% during infections, whereas gcHnf4α overexpression enhanced larval survival by 17.78–23.33% in single or coinfection scenarios." (PMID 40920830, 2025). "A common motif comprised of the genes IKBKE, C1QBP, and EHHADH was found to be directly connected to the HNF4A hub in the infection tolerant state associated with A. baumanii and K. pneumoniae infection." (PMID 35706367, 2022). "Furthermore, infection with HCV led to loss of HNF4α by inducing the upregulation of miR-24 and miR-629 with concurrent downregulation of miR-124 expression levels." (PMID 34771521, 2021). "Functional validation demonstrates that Hnf4α overexpression enhances survival across infection types, while genetic ablation abolishes anti-pathogen defenses." (PMID 40920830, 2025). "In summary, while HBV infection appears to decrease the levels of HNF4α in long-term infection, HNF4α itself is important for HBV replication." (PMID 34771521, 2021). "Antifibrotic regulator hepatic nuclear factor 4‐alpha, HNF4A was significantly activated as a result of infection." (PMID 34582586, 2021). "An early, an intermediate and a late time point (7, 13, and 31 days post infection (dpi), respectively) were selected to analyze the HNF4α level." (PMID 32023898, 2020). "After 6 weeks of infection, however, the level of HNF4α was strongly suppressed in the livers of all infected mice (right)." (PMID 32023898, 2020). "Persistent HBV infection remarkably attenuated the HNF4α protein level in mice livers at 26 weeks post infection." (PMID 32023898, 2020). "The mRNA levels of NRF2 and STAT3 were found to be increased in a time-dependent manner in HCV-infected PHHs, whereas HNF4A mRNA levels were decreased over time post infection." (PMID 31547152, 2019). "To further investigate the role of HNF4α in liver metabolism, we overexpressed HNF4α in rat primary hepatocytes by Ad-rHNF4α infection and analyzed the expression of liver-related genes by PCR array." (PMID 22190905, 2011). "In vivo assays showed that gcHnf4α overexpression significantly improved larval survival during A. salmonicida, GCRV-II, or coinfection, while hnf4α knockout led to drastically reduced survival, confirming Hnf4α’s critical protective role across infection types." (PMID 40920830, 2025). "In addition, viral nucleocapsid (NC) staining was detected in HNF4α positive cells at 48 h post-infection." (PMID 36128218, 2022). "The expression level of HNF4α was suppressed in long-term infection of HBV in the mouse model." (PMID 32023898, 2020). "In these cells, the levels of HNF1α and HNF4α were gradually decreasing after infection." (PMID 32793175, 2020). "However, significant reduction of HNF4α protein level was observed at 13 dpi and the HNF4α inhibitory effect of HBV infection was greater at the end of the infection course (31 dpi)." (PMID 32023898, 2020). "We found that the expression level of HNF4α was suppressed by HBV only in long-term infection." (PMID 32023898, 2020). "Researchers have explored the potential of reducing infection by lowering HNF4α levels in mice, which revealed that siRNA knockdown of HNF4α prevents HBV replication and reduced pre-genomic RNA levels, but also impaired glucose homeostasis and growth of the cells." (PMID 32019103, 2020). "We hypothesize that the role of HNF1α and its transcriptional co-factor HNF4α in the regulation of fucosylation is an essential part of mounting an acute phase response to infection in humans." (PMID 21203500, 2010). "Following infection of YCC3 cells with sgRNAs targeting HNF4A promoter P1 or promoter P2, we measured the expression of these two HNF4A transcript isoforms using isoform-specific primers." (PMID 33499898, 2021).
infection (continued). "At 6 weeks post infection, the level of HBx protein was undetectable in all HBV-infected mice by Western blot, implying that the effect of HBx in reduction of HNF4α during long-term HBV infection is cumulative and long-lasting." (PMID 32023898, 2020). "The binding of ERα was confirmed to affect the binding affinity of HNF4α for the ENI site and is a proposed mechanism for viral load and infection incidence disparity between males and females." (PMID 32019103, 2020). "Based on the strong suppression of HNF4α in mice expressing HBV, we further seek the effect of HBV infection on HNF4α level using two different infection models." (PMID 32023898, 2020). "Thus, in this study, we sought to examine whether induced hepatocyte-like (iHep) cells, which were directly induced from mouse dermal fibroblasts by infection with a retrovirus expressing Hnf4α and Foxa3, possess the potential for lipid metabolism, similar to hepatocytes." (PMID 25364750, 2014). "Importantly, increased activation of endogenous HNF4A, a member of FHH and a master regulator of hepatic functional genes, was detected in HDFs five days after infection, suggesting an accelerated activation of the endogenous TF." (PMID 36068222, 2022). "Furthermore, antifibrotic regulator hepatic nuclear factor 4‐alpha, HNF4A was significantly activated as a result of infection, but suppressed in fibrotic fish." (PMID 34582586, 2021). "As previous studies from animal and clinical tissues showed that HNF4α levels were markedly decreased in HCC liver tissues, we tested whether infection of HBV affects HNF4α levels in hepatocytes." (PMID 25238230, 2014). "During infection and consistent with other liver injury models, SOX9 expression occurred within activated HSCs in the granuloma scar, cholangiocytes demonstrating ductal hyperplasia, and injured hepatocytes as determined by co-localisation with the hepatocyte specific marker HNF4α." (PMID 40489560, 2025). "Importantly, in mice infected with HBV genotype A, B or C, regardless of genotype variation, the HNF4α level was plunged at six weeks post infection." (PMID 32023898, 2020). "To determine the utility of 3D-HepLPCs-Hep as an infection model for HBV, we evaluated the expression of known host factors essential for HBV infection and replication, including the transcription factors retinoid X receptor A (RXRA), HNF4A, and the viral receptor NTCP." (PMID 30361550, 2019).
metabolic disease (27 papers, 2013 to 2025). A congenital disorder (due to inherited enzyme abnormality) or acquired (due to failure of a metabolically important organ) disorder resulting from an abnormal metabolic process. "We determined that lauric acid was the specific FA catalyzed by Acsm3, and the mitochondrial dysfunction and metabolic disorders caused by Acsm3 were attributed to its induced activation of the lauric acid/Hnf4α/p38 MAPK pathway." (PMID 38191811, 2024). "The nuclear receptor hepatocyte nuclear factor 4 alpha (HNF4α) is a key regulator of pathways associated with various metabolic diseases." (PMID 23874642, 2013). "HNF4A variants are associated with metabolic diseases including MODY19." (PMID 35017517, 2022). "Otherwise, conditional depletion of HNF4α in adult animals primarily leads to metabolic disorders, particularly affecting lipid homeostasis." (PMID 41595461, 2025). "In general, long-term outcomes of lipid perturbations on metabolic diseases as well as on related morbidity and mortality in patients with HNF4A-MODY, GCK-MODY, HNF1A-MODY, and HNF1B-MODY require future investigations." (PMID 39504571, 2025). "Our findings open up further prospects for exploiting the HNF4A-GIP regulatory loop for the treatment of metabolic disorders." (PMID 35017517, 2022). "With its involvement in lipid metabolism, HNF4A has been demonstrated to be crucial in the gene network of NASH connected to metabolic diseases." (PMID 33363197, 2020). "Given that MODY1 patients display lower circulating triglycerides as part of their pathological phenotype, the hepatic contribution of HNF4α to this metabolic disorder is suspected, although remains to be clarified." (PMID 30862908, 2019). "In our study, HNF4A is present in the network of NASH connected to metabolic diseases and regulates HNF1A, an additional transcription regulator also involved in lipid and amino acid metabolism." (PMID 29216278, 2017). "We discovered that HNF4A is the central gene in the network of NASH connected to metabolic diseases and that it regulates HNF1A, an additional transcription regulator also involved in lipid metabolism." (PMID 29216278, 2017). "Berberine, a natural isoquinoline alkaloid, could modulate lipid metabolism and glucose homeostasis by regulating the expression of HNF4α in many metabolic diseases." (PMID 30405404, 2018). "Given that HNF4α is an essential factor both for liver development and function, our results provide a potential mechanistic insight linking prenatal metformin exposure to adult metabolic disorders." (PMID 29215608, 2017).
adenocarcinoma (8 papers, 2009 to 2026). A common cancer characterized by the presence of malignant glandular cells. "Additionally, loss of SMARCA4 was more frequently observed in HNF4α-positive grade 3 adenocarcinomas (2/6, 33%)." (PMID 38710944, 2025). "We speculated the HNF4α expression in grade 3 adenocarcinoma may imply dedifferentiation associated with the inactivated SMARCA4 function, resulting in high-grade morphology and poor prognosis." (PMID 38710944, 2025). "HNF4α-positive adenocarcinomas(n = 33) were divided into two groups: the variant group(15 mucinous, 2 enteric, and 1 colloid), where SMARCA4 was retained in all cases, and the conventional non-mucinous group(6 papillary, 5 solid, and 4 acinar), where SMARCA4 was lost in 3/15 cases(20%)." (PMID 38710944, 2025). "Survival analysis of 230 cases based on histological grading and HNF4α expression revealed that HNF4α-positive poorly differentiated (grade 3) adenocarcinoma showed the worst prognosis." (PMID 38710944, 2025). "All samples of mucinous (15/15, 100%), enteric (2/2, 100%), and colloid (1/1, 100%) adenocarcinoma exhibited HNF4α expression." (PMID 38710944, 2025). "HNF4α expression was detected in a proportion of acinar (4/24, 17%), papillary (6/123, 5%), and solid (5/43, 12%) adenocarcinomas." (PMID 38710944, 2025). "For HNF4A expression alone, the 17 patients previously diagnosed with primary adenocarcinoma (cohort III-B) exhibited positive immunohistochemical staining, thus confirming their primary status." (PMID 28583188, 2017). "RT-PCR confirmed that amphiregulin (Areg), epiregulin (Ereg), fetuin beta (Fetub), claudin 2 (Cldn2), hepatic nuclear factor 4, alpha (Hnf4α), glutathione S-transferase, alpha 4 (Gsta4) and forkhead box A3 (Foxa3) were up-regulated in adenocarcinoma." (PMID 19812696, 2009). "Consistent with Hnf4α mRNA levels the Hnf4α protein levels were elevated in dysplasia as compared to adenocarcinomas." (PMID 19812696, 2009). "The A549 cell line may be considered a representative cell line of HNF4α-positive grade 3 adenocarcinomas." (PMID 38710944, 2025). "Although the loss of SMARCA2 was not significantly more frequent in HNF4α-positive adenocarcinomas, two of the four HNF4α-positive Grade 3 adenocarcinomas that expressed SMARCA4 showed the loss of SMARCA2." (PMID 38710944, 2025). "Data in the Oncomine database revealed that mRNA expression and DNA copy number variation of HNF4A were significantly higher in GC tissues than in normal tissues in TCGA Gastric, Deng Gastric, Cho Gastric, and DErrico Gastric (P < 0.01), especially for intestinal type adenocarcinomas (P < 0.01)." (PMID 33710810, 2021). "In the present study (mostly Asian cases), the frequency of KRAS mutations was significantly higher in HNF4α-positive adenocarcinomas (39.4%, 13/33 cases) than in HNF4α-negative adenocarcinomas (9.2%, 19/207 cases)." (PMID 38710944, 2025). "Note that, unlike HNF4α, loss of SMARCA4 was not an independent prognostic factor in grade 3 adenocarcinomas in our study (Online Resource 6), but we did not investigate the mutational status of SMARCA4 in SMARCA4-retained adenocarcinomas." (PMID 38710944, 2025). "Both the expression of HNF4α and the loss of SMARCA4 are considered characteristics of non-TRU-type adenocarcinomas, but their relationship remains unclear." (PMID 38710944, 2025). "None of the in-situ non-mucinous, minimally invasive, or lepidic adenocarcinoma samples (WHO grade 1), representing TRU-type adenocarcinomas, exhibited HNF4α expression." (PMID 38710944, 2025).
liver (7 papers, 2013 to 2025). "We transplanted bone marrow MSCs overexpressing HNF-4α (HNF-4α-MSCs) into mice with chronic liver injury caused by CCl4." (PMID 31133062, 2019). "Our previous study demonstrated that zinc supplementation restored ethanol-inactivated PPAR-α and HNF-4α, leading to attenuation of alcoholic fatty liver." (PMID 24155903, 2013). "Furthermore, the upregulation of bile acid synthetic enzymes CYP7B1 and CYP8B1 may be attributed, at least in part, to FXR reduction, which is associated with increased expression of their suppressors HNF4α and LRH-1 in human obstructive cholestatic liver." (PMID 25798860, 2015). "Remarkably, HNF4α and CK19 biphenotypic cells were detected in CDE liver tissue, indicating that CK19-positive HPCs can differentiate into hepatocytes in chronic liver injury induced by CDE diet treatment." (PMID 30604254, 2019). "Despite many studies on the significance of HNF4α as an important target in preventing and treating liver malignancies, further investigations are still required to understand the mechanism and the correlation between CLA and HNF4α in regulating and inhibiting EMT." (PMID 36132168, 2022).
gastrointestinal disease (5 papers, 2009 to 2023). A disease that occurs in the gastrointestinal system, excluding the hepatobiliary system. "Hepatocyte nuclear factor 4, HNF4A, is a transcription factor known to play a major role in liver and gastrointestinal diseases." (PMID 33281715, 2020). "IPA analysis revealed enrichments of genes involved in gastrointestinal diseases as well as HNF4a regulation." (PMID 28413451, 2017). "Future studies will be required to elucidate all the underlying mechanisms but it is anticipated that several will be important in diagnosing and treating gastrointestinal diseases involving HNF4α." (PMID 27166517, 2016). "Furthermore, IPA analysis predicted effects on gastrointestinal diseases (P values of 6.25E−4–4.64E−13) and showed a strong enrichment in the upstream regulator HNF4a (P = 2.49E−6), a transcription factor known to be involved in gastrointestinal development." (PMID 28413451, 2017).
gastrointestinal disorders (4 papers, 2016 to 2023). "HNF4A is a critical factor in liver function and digestive diseases." (PMID 29357938, 2018).
kidney disease (3 papers, 2024 to 2025). "The aim of the present work was to investigate the role of HNF4A during acute and chronic human kidney disease and the loss of the mature PT phenotype in cultured PT cells." (PMID 39954965, 2025). "Taken together, these results demonstrate that HNF4A expression is gradually reduced during kidney disease progression, with a parallel gain in VIM expression." (PMID 39954965, 2025). "Top healthy-promoting TFs included canonical PT TFs, HNF4A and PPARA, as well as other factors that have been demonstrated to be protective against kidney disease: ESRRG and RREB149,56–58." (PMID 38347009, 2024).
bacterial infection (2 papers, 2016 to 2025). "Despite these insights, the role of piscine Hnf4α in bacterial infection and bacterial-viral coinfection—common challenges in aquaculture—remains uncharacterized." (PMID 40920830, 2025). "While mammalian HNF4α is well-documented to bind overlapping sequences in the HBV enhancer II to promote viral core promoter activity and HBV replication, its role in bacterial infection and bacterial-viral coinfection has remained unclear." (PMID 40920830, 2025).